MIR3171HG (MIR3171 host gene)
Synonyms: RPS27A_7_1343; RPS27AP4
Gene: Transcribed processed pseudogene on chromosome 14 (27,258,717 to 27,259,166, reverse strand). Ensembl gene ENSG00000258932.
Diseases named in the same sentence as MIR3171HG in open-access papers:
MIR3171HG is named in the same sentence as 2 diseases in open-access papers, as found by Europe PMC text mining. Sharing a sentence is not in itself a finding about the gene and the disease.
MIR3171HG shares sentences with these, for which no sentence is quoted: cancer (1 paper); psychiatric disorder (1).